OR2T29 (olfactory receptor family 2 subfamily T member 29)
Description:
Odorant receptor.
Tractability: Small molecule: it belongs to a druggable protein family. Antibody: UniProt places it where antibodies can reach, with medium confidence; UniProt predicts a signal peptide or a membrane-spanning region; its Gene Ontology location is reachable by antibodies, with medium confidence.
Gene: Protein-coding gene on chromosome 1 (248,556,912 to 248,562,772, reverse strand). Ensembl gene ENSG00000182783.
Subcellular location: Cell membrane
Pathways (Reactome):
Sensory Perception: Expression and translocation of olfactory receptors
Gene Ontology:
Molecular function: olfactory receptor activity; G protein-coupled receptor activity
Biological process: detection of chemical stimulus involved in sensory perception of smell; G protein-coupled receptor signaling pathway
Cellular component: plasma membrane; membrane
Genetic constraint (gnomAD): Missense variants: 4 observed, 16.98 expected, observed/expected ratio (o/e) 0.24, 90% interval 0.12 to 0.54. Synonymous variants: 1 observed, 4.47 expected, observed/expected ratio (o/e) 0.22, 90% interval 0.078 to 1.05.
Homologues: Orthologues: dog OR2T4D (84% identical), dog OR2T4C (83% identical), dog OR2T4B (82% identical), mouse Or2t29 (79% identical), mouse Or2t46 (77% identical), mouse Or2t48 (77% identical), rat Olr1428 (77% identical), mouse Or2t49 (77% identical), mouse Or2t47 (76% identical), rat Or2t47 (76% identical), dog OR2T4G (75% identical), mouse Or2t43 (75% identical), and 4 more. Paralogues in human: OR2T5 (99% identical), OR2T4 (90% identical), OR2T10 (70% identical), OR2T3 (65% identical), OR2T2 (65% identical), OR2T35 (65% identical), OR2T34 (64% identical), OR2T11 (63% identical), OR2T1 (62% identical), OR2T27 (61% identical), OR2T6 (58% identical), OR2T33 (53% identical), and 80 more.